EIF3CL (eukaryotic translation initiation factor 3 subunit C like)
Description:
Component of the eukaryotic translation initiation factor 3 (eIF-3) complex, which is required for several steps in the initiation of protein synthesis. The eIF-3 complex associates with the 40S ribosome and facilitates the recruitment of eIF-1, eIF-1A, eIF-2:GTP:methionyl-tRNAi and eIF-5 to form the 43S pre-initiation complex (43S PIC). The eIF-3 complex stimulates mRNA recruitment to the 43S PIC and scanning of the mRNA for AUG recognition. The eIF-3 complex is also required for disassembly and recycling of post-termination ribosomal complexes and subsequently prevents premature joining of the 40S and 60S ribosomal subunits prior to initiation. The eIF-3 complex specifically targets and initiates translation of a subset of mRNAs involved in cell proliferation, including cell cycling, differentiation and apoptosis, and uses different modes of RNA stem-loop binding to exert either translational activation or repression.
Tractability: PROTAC: ubiquitination databases record sites on it.
Gene: Protein-coding gene on chromosome 16 (28,379,397 to 28,403,846, reverse strand). Ensembl gene ENSG00000205609.
Subcellular location: Cytoplasm
Subcellular location (Human Protein Atlas): Cytosol
Gene Ontology:
Molecular function: protein binding; translation initiation factor activity; translation initiation factor binding; RNA binding
Biological process: translational initiation; cytoplasmic translational initiation; formation of cytoplasmic translation initiation complex
Cellular component: eukaryotic translation initiation factor 3 complex; cytoplasm; eukaryotic 43S preinitiation complex; eukaryotic 48S preinitiation complex
Homologues: Orthologues: macaque EIF3C (99% identical), rabbit EIF3C (98% identical), guinea pig EIF3C (98% identical), mouse Eif3c (97% identical), rat Eif3c (96% identical), tropical clawed frog eif3c (81% identical), zebrafish eif3c (77% identical), Drosophila melanogaster eIF3c (52% identical), Caenorhabditis elegans eif-3.C (43% identical). Paralogues in human: EIF3C (99% identical).
Diseases named in the same sentence as EIF3CL in open-access papers:
EIF3CL is named in the same sentence as 3 diseases in open-access papers, as found by Europe PMC text mining. Sharing a sentence is not in itself a finding about the gene and the disease. The quoted sentences say what the papers report.
melanoma (1 paper, 2024). A malignant, usually aggressive tumor composed of atypical, neoplastic melanocytes. "The TWAS detected 27 genes associated with melanoma with p-values less than 0.05 (the top three genes are LOC389458 (RBAK), C16orf73 (MEIOB), and EIF3CL)." (PMID 39061157, 2024).
squamous cell lung carcinoma (1 paper, 2025). A carcinoma arising from squamous bronchial epithelial cells. "Among shared risk genes, THBS3 (thrombospondin 3) and EIF3CL (eukaryotic translation initiation factor 3 subunit C-like) show particularly strong associations with both diseases, possibly representing key molecular nodes connecting RA pathophysiology with squamous cell lung cancer development." (PMID 41327467, 2025).
EIF3CL also shares sentences with these, for which no sentence is quoted: ovarian carcinoma (1 paper).